ENSG00000201410
Synonyms: LOC124906345
Gene: Small nucleolar RNA gene on chromosome 3 (86,125,216 to 86,125,287, forward strand). Ensembl gene ENSG00000201410.
Gene Ontology:
Biological process: RNA processing
Cellular component: nucleolus
Homologues: Paralogues in human: SNORD6 (81% identical).